TIMP4 (TIMP metallopeptidase inhibitor 4)
Description:
Complexes with metalloproteinases (such as collagenases) and irreversibly inactivates them by binding to their catalytic zinc cofactor. Known to act on MMP-1, MMP-2, MMP-3, MMP-7 and MMP-9.
Synonyms: TIMP-4
Tractability: Antibody: UniProt places it where antibodies can reach, with medium confidence; UniProt predicts a signal peptide or a membrane-spanning region; its Gene Ontology location is reachable by antibodies, with medium confidence. PROTAC: ubiquitination databases record sites on it.
Gene: Protein-coding gene on chromosome 3 (12,153,068 to 12,158,912, reverse strand). Ensembl gene ENSG00000157150.
Subcellular location: Secreted
Gene Ontology:
Molecular function: metalloendopeptidase inhibitor activity
Biological process: negative regulation of membrane protein ectodomain proteolysis; response to cytokine; response to hormone; negative regulation of proteolysis
Cellular component: extracellular matrix; extracellular region; secretory granule lumen
Genetic constraint (gnomAD): Loss-of-function variants: 27 observed, 26.65 expected, observed/expected ratio (o/e) 1.01, 90% interval 0.75 to 1.4. The upper end of that interval is the gene's LOEUF score, 1.4, which puts it in group 5 of 6, group 1 being the genes least tolerant of losing a copy. Missense variants: 304 observed, 288.56 expected, observed/expected ratio (o/e) 1.05, 90% interval 0.96 to 1.16. Synonymous variants: 138 observed, 117.53 expected, observed/expected ratio (o/e) 1.17, 90% interval 1.02 to 1.35.
Homologues: Orthologues: chimpanzee TIMP4 (99% identical), macaque TIMP4 (99% identical), rabbit TIMP4 (94% identical), dog TIMP4 (92% identical), rat Timp4 (90% identical), guinea pig TIMP4 (89% identical), mouse Timp4 (89% identical), pig TIMP4 (88% identical), tropical clawed frog timp4 (59% identical), zebrafish timp4.1 (37% identical), zebrafish timp4.3 (27% identical), zebrafish timp4.2 (26% identical). Paralogues in human: TIMP2 (47% identical), TIMP3 (44% identical), TIMP1 (33% identical).
Diseases named in the same sentence as TIMP4 in open-access papers:
TIMP4 is named in the same sentence as 174 diseases in open-access papers, as found by Europe PMC text mining. Sharing a sentence is not in itself a finding about the gene and the disease. The quoted sentences say what the papers report.
Obesity (14 papers, 2012 to 2026). Accumulation of substantial excess body fat. "TIMP4 is highly expressed in adipose tissue, and in a study using TIMP4-deficient mice exposed to a high-fat diet, it promoted high-fat-induced obesity, fatty liver, and dyslipidemia." (PMID 35847900, 2022). "TIMP4 is one of the endogenous inhibitors of metalloproteinases associated with remodeling of the extracellular matrix and expandability of the adipose tissue during the development of obesity." (PMID 37432145, 2023). "Considering the multiple protective effects of Timp4 gene deletion against obesity and associated comorbidities, targeted inhibition of TIMP4 could be a promising therapeutic target against obesity." (PMID 28740132, 2017). "In a study investigating nutrient-induced obesity in mice, it was observed that the expression of TIMP4 was downregulated in obese mice." (PMID 40495162, 2025). "TGF-β expression is positively correlated with the expression of TIMP-1, TIMP-3, and TIMP-4 in adipose tissue of people with obesity." (PMID 37383542, 2023). "TIMP4, in particular, was previously shown to be reduced in the visceral fat of obese mice, even though its deletion protects mice from diet-induced obesity." (PMID 37432145, 2023). "TIMP4 is highly expressed in adipose tissue and was reported to promote high fat‐induced obesity, fatty liver, and dyslipidaemia in a study using TIMP4‐deficient mice exposed to high‐fat diet." (PMID 34151535, 2021). "Increased food intake along with decreased BMR should lead to increased body fat and severe obesity, but in contrast, Timp4−/− mice exhibit decreased body fat and reduced obesity following HFD feeding." (PMID 28740132, 2017). "Since Timp4−/− HFD mice showed reduced adiposity and plasma FFAs, we investigated if this led to improved obesity-associated glucose intolerance." (PMID 28740132, 2017). "MMPs are inhibited by endogenous tissue inhibitors (TIMPs), and we here demonstrated upregulation of tissue inhibitors of metalloproteinases TIMP-1 and TIMP-4 with obesity." (PMID 22748184, 2012). "PPARG, ADAMTS5, TIMP4, ANXA1, AGTR1, and CXCL12 genes are evidently associated with obesity, suggesting that the influence of these genes on obesity may be similar to the influence of fat accumulation in hMSCs." (PMID 34899844, 2021). "TIMP4 is highly expressed in adipose tissue, its levels are further elevated following high-fat diet, but its role in obesity is unknown." (PMID 28740132, 2017). "To investigate whether the increase in TIMP4 contributes to adipose tissue fat deposition and obesity, we fed WT and age-matched Timp4−/− mice HFD for 12 weeks." (PMID 28740132, 2017). "This study is the first to report the role of TIMP4 in high-fat diet-induced obesity." (PMID 28740132, 2017). "Obesity was also associated with increased expressions of angiogenesis-related proteins, in particular, angiogenin, endoglin, endostatin, endothelin-1, IGFBP-3, leptin, MMP-3, PAI-1, TIMP-4, CXCL16, platelet factor 4, DPPIV and coagulation factor III." (PMID 22748184, 2012). "Tissue inhibitor of metalloproteinases 4 (Timp4) modulates ECM turnover, and its absence improves obesity and related complications." (PMID 41484887, 2026). "Patients with comorbidities such as hypertension, obesity, and diabetes had elevated DPPIV, MMP-8, and TIMP-4 levels, and reduced MMP-3 and TIMP-2 levels, indicating a link between these markers and the exacerbating effects of comorbidities on COVID-19 outcomes." (PMID 40557167, 2025). "For example, mice lacking TIMP4 resist diet-induced obesity as a result of impaired lipid absorption." (PMID 39747859, 2025). "In obesity, increased TGF-β signalling has been suggested to exert pro-fibrogenic actions by stimulating the expression of tissue inhibitors of metalloproteases (TIMPs), including TIMP-1, TIMP-3, and TIMP-4, and connective tissue growth factor (CTGF)." (PMID 37383542, 2023).
Obesity (continued). "In summary, our study demonstrates that absence of TIMP4 suppresses HFD-induced obesity possibly by impairing lipid absorption." (PMID 28740132, 2017). "Our study reveals that absence of TIMP4 can impair lipid absorption and the high fat diet-induced obesity in mice possibly by regulating the proteolytic processing of CD36 protein in the intestinal enterocytes." (PMID 28740132, 2017). "Absence of TIMP4 ameliorated high-fat-diet-induced obesity in mice." (PMID 39753963, 2025).
breast carcinoma (10 papers, 2008 to 2025). "TIMP4 has been found associated with breast cancer to modulate the ER-α Signalling in MCF7 Breast Cancer Cells." (PMID 37238942, 2023). "TIMP-4 increased expression is associated with human mammary carcinoma, endometrial carcinoma, and gastric cancer, while its expression is diminished in human gliomas and in Wilms ́ tumors." (PMID 26291714, 2015). "Previously, TIMP4 has been demonstrated to be upregulated in breast cancer, prostate cancer, glioblastoma, and head and neck squamous cell carcinoma; whereas, low TIMP4 levels have been observed in patients with pancreatic cancer." (PMID 40291774, 2025). "The genes namely COL11A1, MMP11 and COL10A1 were found up-regulated and PCOLCE2, LAMA2, TMTC1, and TIMP4 were found down-regulated in breast cancer cell lines also." (PMID 37238942, 2023). "We found that LAMA2 and TIMP4 were significantly associated and TMTC1 gene was less correlated with breast cancer occurrence." (PMID 37238942, 2023). "LAMA2 and TIMP4 were found significantly associated and TMTC1 gene was found less correlated with breast cancer occurrence." (PMID 37238942, 2023). "LAMA2 and TIMP4 were significantly associated and TMTC1 gene was less correlated with breast cancer occurrence." (PMID 37238942, 2023). "LAMA2 and TIMP4 were found significantly associated and TMTC1 was found less correlated with breast cancer occurrence." (PMID 37238942, 2023). "regarding breast cancer, in contrast to Wang’s study in which TIMP4 played a role in stimulating tumorigenesis, Jiang’s study showed that TIMP4 inhibited tumour growth and invasion." (PMID 34781885, 2021). "In agreement with our results, previous work has shown that TIMP-4 regulates de expression of Bcl-2 proteins in a breast cancer mouse model." (PMID 26291714, 2015). "Moreover, we further deeply investigated the role of LAMA2, TMTC1 and TIMP4 genes in breast cancer prognosis." (PMID 37238942, 2023). "Changes in TIMP4 expression have been reported to contribute to the development of breast cancer." (PMID 34178671, 2021). "Moreover, TIMP-4 can induce apoptosis in vascular smooth cells and transformed cardiac fibroblasts, although, paradoxically, this factor has also been shown to protect breast cancer cells from apoptosis, implying a tissue-specific effect." (PMID 26291714, 2015). "In conclusion, our study identified nine key regulators, of which COL11A1, MMP11 and COL10A1 were up regulated and PCOLCE2, LAMA2, TMTC1, ADAMTS5, TIMP4 and RSPO3 were down regulated in breast cancer samples as compared to control samples." (PMID 37238942, 2023). "OncoLnc was used to analyse the effect of expression levels of LAMA2, TIMP4, and TMTC1 on the survival of breast cancer patients." (PMID 37238942, 2023). "Expression level of LAMA2, TIMP4, and TMTC1 was higher in all different stages of TCGA breast cancer samples and significantly expressed among different age groups of patients (younger to older age group)." (PMID 37238942, 2023). "OncoLnc was used to analyze the effect of expression levels of LAMA2, TIMP4, and TMTC1 on the survival of breast cancer patients." (PMID 37238942, 2023). "The genes namely COL11A1, MMP11 and COL10A1 were found up regulated and PCOLCE2, LAMA2, TMTC1, ADAMTS5, TIMP4 and RSPO3 were found down regulated in breast cancer." (PMID 37238942, 2023). "Among these key genes COL11A1, MMP11 and COL10A1 were highly expressed and PCOLCE2, LAMA2, TMTC1, ADAMTS5, TIMP4, and RSPO3 were having lower expression levels in breast cancer samples." (PMID 37238942, 2023). "Up-regulated expression of COL10A1, MMP11, CST1, GJB2, MMP1, MMP13, and CEACAM6; down-regulated expression of ADH1B, CIDEC, THRSP, GPD1, TIMP4, FABP4, and SCARA5 genes was common in breast cancers of the two populations." (PMID 31292488, 2019). "Two genes (DAXX, ADAM17) are involved in ovarian cancer and three genes (TNFRSF1A, TIMP4, COL1A2) are exclusive to breast cancer." (PMID 31205821, 2019).
breast carcinoma (continued). "A previous study showed that TIMP4 secretion was regulated by the expression of LOX/SNAI2 axis and contributed to the malignant phenotype of cancers, e.g., thyroid cancer, colon cancer, and breast cancer." (PMID 31795200, 2019). "Since TIMP-4 was not measured, no conclusion regarding TIMP-4 correlation with breast cancer progression can be made, although further studies on the possible dual role of this inhibitor are warranted." (PMID 19025595, 2008).
myocardial infarction (10 papers, 2016 to 2025). Gross necrosis of the myocardium, as a result of interruption of the blood supply to the area, as in coronary thrombosis. "A study about cardiovascular disease has demonstrated that TIMP4 deficient mice are more susceptible to myocardial infarction, a high mortality rate induced by myocardial infarction is detected." (PMID 37328892, 2023). "Interestingly, researchers discovered that in Timp4-defect animal models, its loss moderately compromised cardiac functions with aging, and gene-defect animals exhibited a higher susceptibility to mortality in induced myocardial infarction." (PMID 38069250, 2023). "A previous study reported that the TIMP-4 level increased soon after acute myocardial infarction (AMI) and was positively correlated with left ventricular volume changes." (PMID 39992996, 2025). "TIMP-4 is highly expressed in the cardiac tissue and was reduced in myocardial infarction and ischemic cardiomyopathy." (PMID 35109843, 2022). "Interestingly, Timp4−/− mice are more vulnerable to myocardial infarction." (PMID 30926607, 2019). "Four days post-acute myocardial infarction, TIMP-4 was elevated and correlated positively with the occurrence of major adverse cardiac events, but in subjects with ischemic or idiopathic dilated cardiomyopathy, myocardial protein levels of TIMP-4 were reduced." (PMID 35265689, 2022).
diabetes (8 papers, 2010 to 2025). "Therefore, MMP-2, MMP-9, MMP-11, MMP-13, and TIMP-4 could be important biomarkers to evaluate in diabetes and associated disorders." (PMID 33419373, 2020). "Hypertension and diabetes were associated with increases in several MMPs/TIMPs, particularly MMP-3 and TIMP-4." (PMID 23967183, 2013). "Based on our findings, we conclude that in diabetes, HHcy antagonizes PPARγ and induces production of oxygen radicals that enhances MMP-9 and inhibits TIMP-4, which in turn causes matrix remodeling, E-M uncoupling and fibrosis impairing diastolic functions." (PMID 20828387, 2010). "Interestingly, diabetes-related alterations of the extracellular matrix and adhesion molecules were varied; Pecam, Mmp10, Lamc1, Itgb7, Mmp9, and Timp4 were up-regulated, but Col11a1, Fn1, Admts2, and Itgav were down-regulated." (PMID 21984919, 2011). "We hypothesize that E-M uncoupling in diabetes is due in part to increased level of homocysteine causing activation of latent MMP-9, attenuation of thioredoxin and TIMP-4 in response to antagonizing PPARγ." (PMID 20828387, 2010). "Comparing healthy diabetics to those with cardiovascular complications revealed a reduction in EG-VEGF and TIMP-4 (in addition to LAP (TGF-b1), Leptin, PD-ECGF, and Serpin F1) in all patients with diabetes with CAD while TIMP-1 was significantly increased." (PMID 35109843, 2022).
heart failure (8 papers, 2016 to 2026). Inability of the heart to pump blood at an adequate rate to meet tissue metabolic requirements. "In animal model-based studies, an increase in TIMP-4 was observed in compensated left ventricular hypertrophy, but in heart failure, TIMP-4 level or activity had decreased." (PMID 39992996, 2025). "TIMP-1 is induced in heart failure, and TIMP-4 is highly expressed in the heart and is decreased during chronic cardiac failure." (PMID 39727952, 2024). "An upregulation of TIMP1 and downregulation of TIMP4 has been observed by others in the working myocardium in various species and heart failure models." (PMID 37122221, 2023). "MMP2/TIMP4 ratio has been reported to be increased in heart failure induced by occlusion of the left coronary artery in spontaneously hypertensive rats." (PMID 33129260, 2020). "In conclusion, our data clearly indicated that there is epigenetic silencing of TIMP4 in heart failure and strengthens the concept that if administered exogenously or overexpressed in the heart tissue, it can contribute significantly to cardioprotection." (PMID 27396717, 2016). "This study aims to determine the mechanism of silencing of TIMP4 in heart failure progression created by aorta‐vena cava (AV) fistula." (PMID 27396717, 2016). "We observed that there are 7 CpG islands in the TIMP4 promoter which get methylated during the progression of heart failure which leads to its epigenetic silencing." (PMID 27396717, 2016). "Since the mRNA levels of TIMP4 go down in heart failure, we hypothesize that there is epigenetic silencing of TIMP4 in terms of methylation of the promoter, histone acetylation and microRNA122a." (PMID 27396717, 2016). "This is a novel report to explain the epigenetic silencing of TIMP4 in heart failure." (PMID 27396717, 2016). "Although studies show that the expression of TIMP4 goes down in heart failure but the mechanism is unknown." (PMID 27396717, 2016). "In this study, we speculate that there is epigenetic silencing of TIMP4 in heart failure which allows the MMP9 to increase." (PMID 27396717, 2016). "We hypothesize that in heart failure these CpG islands get methylated which leads to the silencing of the TIMP4 gene." (PMID 27396717, 2016). "Furthermore, genes for fibrotic regulators, such as TGFβ1, TIMP1, TIMP3, TIMP4, and ADAMTS1, were linked to CLIC expression, reinforcing the hypothesis that CLICs contribute to fibrotic progression and ECM remodeling in human heart failure." (PMID 41521401, 2026). "We hypothesize that there is epigenetic silencing of TIMP4 in heart failure." (PMID 27396717, 2016). "The tissue inhibitor of matrix metalloproteinase 4 (TIMP4) is a modulator of matrix metalloprotease 9 (MMP9), which regulates the pathological cardiac remodelling process, and it has been demonstrated that TIMP4 is reduced in heart failure." (PMID 39596076, 2024). "Although studies report that TIMP4 goes down in heart failure 23, there are no reports in heart which show the mechanism of TIMP4 down‐regulation." (PMID 27396717, 2016).
glioma (7 papers, 2001 to 2024). A benign or malignant brain and spinal cord tumor that arises from glial cells (astrocytes, oligodendrocytes, ependymal cells). "Among tissue MMP inhibitors, TIMP4 appeared to be the only one overexpressed in malignant forms of gliomas." (PMID 38474106, 2024). "TIMP4 is also downregulated during human herpesvirus 6 (HHV-6) promotion of glioma development and progression." (PMID 34781885, 2021). "Regarding the relationship between TIMP4 and glioma progression, the directivity of the available findings is inconsistent." (PMID 34781885, 2021). "Research conducted on human gliomas has shown that TIMP-4 substantially reduced glioma’s invasive capacity, although without decreased cell viability and proliferation." (PMID 30062663, 2019). "Recombinant TIMP-4 reduced invasion of U251 glioma cells through Matrigel, and U87 clones overexpressing TIMP-4 showed reduced invasive capacity in vitro." (PMID 11437402, 2001). "TIMP4, a biomarker for astrocytoma in glioma patients, was highly expressed in CHLA-02." (PMID 35954348, 2022). "In contrast, the observed decrease of TIMP-4 level is difficult to explain and reconcile with CBD antitumor effects, since the only study addressing the role of TIMP-4 in gliomas reported a negative correlation between TIMP-4 level and the grade of the disease." (PMID 24204703, 2013).
dementia (6 papers, 2022 to 2024). Loss of intellectual abilities interfering with an individual's social and occupational functions. "Most delirium patients had pre-existing dementia and low TIMP-4 is the only marker associated with delirium in adjusted analyses." (PMID 38937571, 2024). "Compared to the CU reference group, cognitive impairment at the MCI stage was associated with increased levels of TIMP-2 and TIMP-4, whereas the dementia stage was associated with increased levels of MMP-10 and TIMP-2." (PMID 37221606, 2023). "Moreover, higher baseline plasma TIMP4 levels in dementia-free people are associated with long-term risk of dementia." (PMID 38915119, 2024). "NEFL and TIMP4 were also consistently dysregulated in all types of dementia in a PEA-based study in the Massachusetts Alzheimer’s Disease Research Center cohort." (PMID 37175824, 2023). "Proteins SAP3, NPS‐PLA2, IGFBP‐7, MIC‐1, TIMP‐4, and OPG have been reported to be associated with dementia in case‐control studies, and TREM2 and N‐terminal pro‐BNP in prospective cohort studies, with all associations in the same direction as in this study." (PMID 34338426, 2022). "Increased plasma TIMP4 levels have been measured (at baseline) in patients with mild cognitive impairment (MCI) that converted to dementia within 5 years, in comparison to MCI patients that did not progress." (PMID 38915119, 2024).